HSF1 (heat shock transcription factor 1)
Description:
Functions as a stress-inducible and DNA-binding transcription factor that plays a central role in the transcriptional activation of the heat shock response (HSR), leading to the expression of a large class of molecular chaperones, heat shock proteins (HSPs), that protect cells from cellular insult damage. In unstressed cells, is present in a HSP90-containing multichaperone complex that maintains it in a non-DNA-binding inactivated monomeric form. Upon exposure to heat and other stress stimuli, undergoes homotrimerization and activates HSP gene transcription through binding to site-specific heat shock elements (HSEs) present in the promoter regions of HSP genes. Upon heat shock stress, forms a chromatin-associated complex with TTC5/STRAP and p300/EP300 to stimulate HSR transcription, therefore increasing cell survival. Activation is reversible, and during the attenuation and recovery phase period of the HSR, returns to its unactivated form. Binds to inverted 5'-NGAAN-3' pentamer DNA sequences. Binds to chromatin at heat shock gene promoters. Activates transcription of transcription factor FOXR1 which in turn activates transcription of the heat shock chaperones HSPA1A and HSPA6 and the antioxidant NADPH-dependent reductase DHRS2. Also serves several other functions independently of its transcriptional activity. Involved in the repression of Ras-induced transcriptional activation of the c-fos gene in heat-stressed cells. Positively regulates pre-mRNA 3'-end processing and polyadenylation of HSP70 mRNA upon heat-stressed cells in a symplekin (SYMPK)-dependent manner. Plays a role in nuclear export of stress-induced HSP70 mRNA. Plays a role in the regulation of mitotic progression. Also plays a role as a negative regulator of non-homologous end joining (NHEJ) repair activity in a DNA damage-dependent manner. Involved in stress-induced cancer cell proliferation in a IER5-dependent manner. (Microbial infection) Plays a role in latent human immunodeficiency virus (HIV-1) transcriptional reactivation. Binds to the HIV-1 long terminal repeat promoter (LTR) to reactivate viral transcription by recruiting cellular transcriptional elongation factors, such as CDK9, CCNT1 and EP300.
Synonyms: HSTF1
Tractability: Small molecule: a high-quality ligand is known. PROTAC: UniProt records ubiquitination sites on it; ubiquitination databases record sites on it; its protein half-life has been measured; a small molecule that binds it is known.
Target class: Other cytosolic protein
Gene: Protein-coding gene on chromosome 8 (144,291,529 to 144,314,727, forward strand). Ensembl gene ENSG00000185122.
Subcellular location: Nucleus; Cytoplasm; Nucleus, nucleoplasm; Cytoplasm, perinuclear region; Cytoplasm, cytoskeleton, spindle pole; Cytoplasm, cytoskeleton, microtubule organizing center, centrosome; Chromosome, centromere, kinetochore
Subcellular location (Human Protein Atlas): Nucleoplasm; Cytosol
Pathways (Reactome):
Cellular responses to stimuli: Attenuation phase; HSF1 activation; HSF1-dependent transactivation; Mitochondrial unfolded protein response (UPRmt); Regulation of HSF1-mediated heat shock response
Autophagy: Aggrephagy
Gene Ontology:
Molecular function: chromatin DNA binding; DNA binding; DNA-binding transcription activator activity, RNA polymerase II-specific; DNA-binding transcription factor activity, RNA polymerase II-specific; DNA-binding transcription repressor activity, RNA polymerase II-specific; general transcription initiation factor binding; heat shock protein binding; Hsp90 protein binding; identical protein binding; protein binding; protein heterodimerization activity; protein kinase binding; RNA polymerase II cis-regulatory region sequence-specific DNA binding; RNA polymerase II intronic transcription regulatory region sequence-specific DNA binding; sequence-specific DNA binding; sequence-specific double-stranded DNA binding; transcription cis-regulatory region binding; translation elongation factor binding; DNA-binding transcription factor activity; chromatin binding
Biological process: cellular response to cadmium ion; cellular response to copper ion; cellular response to diamide; cellular response to gamma radiation; cellular response to heat; cellular response to sodium arsenite; cellular response to unfolded protein; MAPK cascade; negative regulation of double-strand break repair via nonhomologous end joining; negative regulation of protein-containing complex assembly; negative regulation of transcription by RNA polymerase II; positive regulation of macrophage differentiation; positive regulation of mitotic cell cycle; positive regulation of transcription by RNA polymerase II; protein-containing complex assembly; regulation of cellular response to heat; regulation of transcription by RNA polymerase II; positive regulation of cold-induced thermogenesis; positive regulation of gene expression; regulation of DNA-templated transcription
Cellular component: centrosome; cytoplasm; cytosol; kinetochore; mitotic spindle pole; nuclear stress granule; nucleoplasm; nucleus; perinuclear region of cytoplasm; PML body; protein folding chaperone complex; ribonucleoprotein complex; chromatin; pronucleus; protein-containing complex; spindle pole
Genetic constraint (gnomAD): Loss-of-function variants: 29 observed, 44.73 expected, observed/expected ratio (o/e) 0.65, 90% interval 0.48 to 0.88. The synonymous counts are far from expectation, so gnomAD's model fits this gene poorly and the ratio says little. Missense variants: 675 observed, 648.51 expected, observed/expected ratio (o/e) 1.04, 90% interval 0.98 to 1.11. Synonymous variants: 365 observed, 280.34 expected, observed/expected ratio (o/e) 1.3, 90% interval 1.19 to 1.42.
Homologues: Orthologues: chimpanzee HSF1 (99% identical), macaque HSF1 (94% identical), dog HSF1 (92% identical), mouse Hsf1 (90% identical), rat Hsf1 (90% identical), pig HSF1 (89% identical), guinea pig HSF1 (88% identical), rabbit HSF1 (84% identical), tropical clawed frog hsf1 (65% identical), Drosophila melanogaster Hsf (32% identical), Caenorhabditis elegans hsf-1 (29% identical). Paralogues in human: HSF2 (37% identical), HSF4 (35% identical), HSF5 (15% identical), HSFY1 (14% identical), HSFY2 (14% identical), HSFX1 (12% identical), HSFX2 (12% identical), HSFX4 (11% identical), HSFX3 (11% identical).
Diseases named in the same sentence as HSF1 in open-access papers:
HSF1 is named in the same sentence as 246 diseases in open-access papers, as found by Europe PMC text mining. Sharing a sentence is not in itself a finding about the gene and the disease. The quoted sentences say what the papers report.
breast cancer (121 papers, 2010 to 2025). A primary or metastatic malignant neoplasm involving the breast. "HSF1 deficiency has been shown to reduce the proliferation of mammary tumors having dysfunctional HR due to BRCA1 mutations." (PMID 39850800, 2024). "Elevated nuclear levels of HSF1 have been linked to increased tumor growth, lymph node invasion, and death in cases of breast cancer, particularly in individuals who test positive for the estrogen receptor (ER)." (PMID 38339390, 2024). "The METABRIC data cohort identified a significant correlation between overexpression of CD44/ALDH1A1 and HSP90 or HSF1 in patients with HER2-positive breast cancer, which was associated with relatively poorer overall survival." (PMID 38646654, 2024). "Intriguingly, a study in breast cancer mentioned that overexpression of HSF1 in ERα-positive breast cancer is associated with decreased reliance on the ERα-controlled transcription program for cancer growth." (PMID 37958341, 2023). "In a meta-analysis of 10 studies, including 3159 patients, HSF1 protein abundance was also associated with shorter overall survival in esophageal squamous cell carcinoma, breast cancer, HCC, as well as non-small cell lung cancer (NSCLC) and pancreatic cancer." (PMID 35311075, 2022). "Here, we show that high levels of the stress response master regulator, the heat shock factor 1 (HSF1), are associated with antiestrogen resistance in breast cancer cells." (PMID 33593922, 2021). "In summary, we are proposing that overexpression of HSF1 in ERα-positive breast cancers is associated with a decrease dependency on the ERα-controlled transcriptional program for cancer growth." (PMID 33593922, 2021). "Recent studies have shown that HSF1 is associated with advanced tumor progression and poor prognosis in gastric cancer and breast cancer." (PMID 33946531, 2021). "The association between overexpression of HSF1 and poor prognosis in breast cancer is linked with Lapatinib (HER2 and EGFR inhibitor) and Trastuzumab (HER2 antibody) resistance." (PMID 33593922, 2021). "Taken together, these results establish that progression toward an endocrine resistance phenotype in breast cancer is associated with an increase in HSF1 and a decrease in ERα transcriptional activity." (PMID 33593922, 2021). "Phosphorylation of HSF1 at serine 326 is associated with HSF1 activation, and in ERα-positive breast cancer, HSF1 upregulates the expression of HSP90/HSPC, a chaperone that aids in the maturation of ERα and numerous kinases that drive tumorigenesis." (PMID 32408596, 2020). "Especially, a high HSF1 level was associated with an increased mortality of estrogen receptor-positive (ER+) breast cancer patients." (PMID 31614463, 2019). "In early stage breast cancer, high stromal Heat Shock Factor 1 (HSF1) activation is associated with poor outcome and experimental data show that HSF1 expression is elevated/activated and results in potent enabling of malignancy." (PMID 29868579, 2018). "The HSF1 activation in breast cancer cell line (MSF7) was shown to cause elevated expression of HSP60, HSP70 and HSP90 and the cancer cells escaped from apoptotic cell death." (PMID 29494616, 2018). "In breast cancer, a high HSF1 level was associated with histological grade, larger tumour size, and nodal involvement." (PMID 30326922, 2018). "Together, these data suggest AKT and HSF1 are activated in breast cancer stem cells and loss of HSF1 activity reduces the self-renewal of the breast cancer stem cell population." (PMID 29088759, 2017). "Nuclear HSF1 has previously been shown to be associated with poor patient outcomes in breast cancer." (PMID 29088759, 2017). "HSF1 has been shown to be associated with oncogenic functions in several cancer types including breast cancer, hepatocellular carcinoma, and ovarian cancer among several others." (PMID 29088759, 2017).
breast cancer (continued). "An association of HSF1 expression with breast cancer stem cells has been previously observed but our results further indicate S326 phosphorylation and HSF1 activity are critical to its role in these stem cells." (PMID 29088759, 2017). "HSF1 is considered a potential target for anti-cancer therapy because it is overexpressed in several cancers, including breast cancer, and increased expression has been associated with poor prognosis." (PMID 28241425, 2017). "High levels of HSF1 expression in tumor tissues has been reported to be associated with poor progression in patients with breast cancer, endometrial carcinoma, hepatocellular carcinoma and Hodgkin’s lymphoma." (PMID 26511079, 2015). "In agreement, another clinical study found HSF1 upregulation in 80% of breast cancers, which was also associated with high histologic grade and increased mortality." (PMID 25954247, 2015). "High HSF1 expression has been associated with a reduced survival rate of patients with breast cancer and was proposed as an independent prognostic factor for overall survival in patients with hepatocellular carcinoma." (PMID 24467529, 2014). "HSF1, a stress response protein and an activator of heat-shock protein encoding genes, is implicated in breast cancer initiation and progression." (PMID 25969759, 2012). "Because HSF1 is a pro-survival factor associated with resistance to treatment in multiple cancers, development of small-molecule inhibitors is providing the opportunity to test new combinatorial strategies to target resistant breast cancers." (PMID 33593922, 2021). "Some premises indicate that high levels of HSF1 may be associated with resistance of estrogen-dependent breast cancers to hormonal therapies based on antiestrogens." (PMID 34783649, 2021). "Therefore, it is likely that during breast cancer development other signaling pathways activate HSF1 in order to compensate for the loss of HER2 function." (PMID 32408596, 2020). "CAFs in human breast cancer biopsies were shown to be rich in HSF1, and the depletion of HSF1 led to a loss of the factors transforming growth factor-β (TGF-β) and CXCL12/SDF1 known to program the tumor microenvironment in a pro-tumorigenic and metastatic manner." (PMID 32331382, 2020). "HSF1 strong activation is associated with increased tumor grade and poor outcome in breast cancer." (PMID 33096815, 2020). "Genotype and allele frequencies of four SNPs in HSF1 gene and association with breast cancer risk." (PMID 29494616, 2018). "Also, human breast cancer tissue showed high abundance of HSF-1, and decreased level of HSF-1 has been linked to improved cancer prognosis." (PMID 29682483, 2018). "This study was based on the hypothesis that 'genetic polymorphism in HSF1 gene might interfere with its activity and hence influence the development of breast cancer'." (PMID 29494616, 2018). "We hypothesized that single nucleotide polymorphisms (SNPs) in HSF1 gene might affect its expression or function which might have an influence on the development of breast cancer." (PMID 29494616, 2018). "High levels of HSF1 have been associated with poor prognosis in breast cancer." (PMID 27713164, 2016). "Furthermore, HSF1 expression is important for proliferation of cancer cells, as demonstrated by a study showing that higher HSF1 expression in breast tumours is associated a poorer prognosis in breast cancer." (PMID 25708542, 2015). "We hypothesized that WA may target breast cancer susceptibility gene-1 (BRCA1) and heat shock factor 1 (HSF1) in breast cancer cells." (PMID 25969759, 2012). "Increased HSF1 is associated with reduced breast cancer survival." (PMID 25969759, 2012).
breast cancer (continued). "Similar associations between nuclear HSF1 and drug resistance against doxorubicin, paclitaxel, carboplatin, and bortezomib have been previously shown in multiple types of cancer cells, such as breast cancer, hepatocellular carcinoma, melanoma, and multiple myeloma cells." (PMID 38474017, 2024). "For instance, in breast cancer, HSF1 stimulates the growth of the stromal cells within the tumor microenvironment (TME), which in turn influences tumor progression." (PMID 40520012, 2025). "Previous studies have shown that phosphorylation of HSF1 at threonine 120 promotes its binding to the PD-L1 promoter, thereby increasing PD-L1 expression in breast cancer." (PMID 40675964, 2025). "HCC and breast cancer have been shown to depend on HSF1 to sufficiently express lactate dehydrogenase (LDH), where LDH is crucial for glycolytic efficiency and further malignant growth and promotion." (PMID 40287736, 2025). "In another study it was observed that PI3K, through Akt, modulates HSF1 by phosphorylation of serine 326, linking PI3K signaling to HSF1-mediated EMT in HER2-positive breast cancer cells." (PMID 40287736, 2025). "Knockdown of HSF1 in breast cancer cells led to decreased tumor size and increased CD8 + T cell infiltration, which was mediated by CCL5." (PMID 40287736, 2025). "In breast cancer, HSF1 knockdown enhances BAX expression and cisplatin-induced apoptosis, whereas restoring HSF1 expression significantly reduces cisplatin-induced apoptosis." (PMID 39850800, 2024). "For example, it was shown that Akt-dependent activation of HSF1 in HER2-amplified breast cancer cells promotes EMT via direct upregulation of the transcription factor Slug." (PMID 39682216, 2024). "The present study aimed to determine the interactions between Bag‐1 and heat shock proteins (HSPs); namely, HSP90, HSP70 and HSP27, to elucidate their role in promoting heat shock factor‐1 (HSF1)‐dependent survival of breast cancer cells." (PMID 39049197, 2024). "In the present study, CRISPR/Cas9-mediated HSF1 knockdown was successful in 4T1 murine breast cancer cells." (PMID 38589452, 2024). "Analysis of HER2-positive breast cancer datasets reveals a positive correlation between HSF1 and components of the HSP chaperone complex, including HSP90 and HSP70, with simultaneous overexpression linked to poorer clinical outcomes." (PMID 38646654, 2024). "It was found that co-activation of AKT and HSF1 occurs in breast cancer and that their combined targeting using selective inhibitors exhibited a synergistic effect on tumor cells." (PMID 39682216, 2024). "Similar associations with poor overall and relapse-free survival have been observed in breast cancer patients with high HSF1 mRNA expression." (PMID 38339390, 2024). "In a recent study, HSF1 overexpression was identified in the well-established antiestrogen resistant breast cancer cell models LCC2 and LCC9 that were derived from MCF-7 cells in response to selection with tamoxifen and/or fulvestrant." (PMID 38567308, 2024). "We demonstrated that Bag‐1 overexpression promoted HER2 expression in breast cancer cells, thereby resulting in the concurrent constitutive activation of the HSF1–HSP axis." (PMID 39049197, 2024). "We observed clear expression overlap between DYRK2 and HSF1 in clustered cell populations of renal cell carcinoma and colon adenocarcinoma along with breast cancer." (PMID 36622366, 2023). "HSF1 is a protein that has been investigated extensively for its function in the development of breast cancer." (PMID 37958341, 2023). "In breast cancer tissues, low levels of microRNA-615-5p correlated with high levels of HSF1 compared to normal tissues." (PMID 37958341, 2023). "Within the TME, stromal HSF1 activation drives a transcriptional program to promote malignant phenotypes and is related to poor outcome observed in breast cancer and lung cancer patients." (PMID 37153737, 2023).